GDNF (glial cell derived neurotrophic factor)
Description:
Neurotrophic factor that enhances survival and morphological differentiation of dopaminergic neurons and increases their high-affinity dopamine uptake. Acts by binding to its coreceptor, GFRA1, leading to autophosphorylation and activation of the RET receptor. Involved in the development of the neural crest.
Synonyms: ATF; ATF1; ATF2; HFB1-GDNF; HSCR3
Tractability: Small molecule: a structure with a bound ligand is known. Antibody: UniProt places it where antibodies can reach, with high confidence; its Gene Ontology location is reachable by antibodies, with high confidence; UniProt predicts a signal peptide or a membrane-spanning region.
Gene: Protein-coding gene on chromosome 5 (37,812,677 to 37,840,041, reverse strand). Ensembl gene ENSG00000168621.
Subcellular location: Secreted
Subcellular location (Human Protein Atlas): Vesicles; Nucleoplasm; Predicted to be secreted
Pathways (Reactome):
Developmental Biology: Formation of the ureteric bud; NCAM1 interactions; RET signaling
Signal Transduction: RAF/MAP kinase cascade
Gene Ontology:
Molecular function: growth factor activity; protein binding; protein homodimerization activity; chemoattractant activity involved in axon guidance; signaling receptor binding; glial cell-derived neurotrophic factor receptor binding; receptor tyrosine kinase binding
Biological process: glial cell-derived neurotrophic factor receptor signaling pathway; mRNA stabilization; negative regulation of extrinsic apoptotic signaling pathway in absence of ligand; negative regulation of neuron apoptotic process; neural crest cell migration; neural crest cell migration involved in autonomic nervous system development; neuron projection development; positive regulation of branching involved in ureteric bud morphogenesis; positive regulation of cell differentiation; positive regulation of cell population proliferation; positive regulation of transcription by RNA polymerase II; positive regulation of ureteric bud formation; regulation of dopamine uptake involved in synaptic transmission; regulation of gene expression; adult locomotory behavior; branching involved in ureteric bud morphogenesis; commissural neuron axon guidance; dorsal spinal cord development; embryonic organ development; enteric nervous system development; metanephros development; negative regulation of apoptotic process; nervous system development; peristalsis; positive regulation of dopamine secretion; and 14 more
Cellular component: extracellular region; Golgi apparatus
Genetic constraint (gnomAD): Loss-of-function variants: 5 observed, 14.51 expected, observed/expected ratio (o/e) 0.34, 90% interval 0.18 to 0.73. The upper end of that interval is the gene's LOEUF score, 0.73, which puts it in group 2 of 6, group 1 being the genes least tolerant of losing a copy. Missense variants: 246 observed, 287.62 expected, observed/expected ratio (o/e) 0.86, 90% interval 0.77 to 0.95. Synonymous variants: 122 observed, 119.46 expected, observed/expected ratio (o/e) 1.02, 90% interval 0.88 to 1.19.
Homologues: Orthologues: chimpanzee GDNF (100% identical), guinea pig GDNF (98% identical), mouse Gdnf (93% identical), rat Gdnf (93% identical), dog GDNF (91% identical), macaque GDNF (82% identical), pig GDNF (73% identical), rabbit GDNF (73% identical), tropical clawed frog gdnf (64% identical), zebrafish gdnfa (55% identical), zebrafish gdnfb (32% identical). Paralogues in human: NRTN (25% identical), ARTN (23% identical), PSPN (22% identical).
Diseases named in the same sentence as GDNF in open-access papers:
GDNF is named in the same sentence as 299 diseases in open-access papers, as found by Europe PMC text mining. Sharing a sentence is not in itself a finding about the gene and the disease. The quoted sentences say what the papers report.
Parkinson disease (247 papers, 2004 to 2026). A progressive degenerative disorder of the central nervous system characterized by loss of dopamine producing neurons in the substantia nigra and the presence of Lewy bodies in the substantia nigra and locus coeruleus. "It is important to note that the mechanisms underlying GDNF’s role in the emergence and progression of early cognitive impairment in Parkinson’s disease are complex; thus, further comprehensive studies are warranted." (PMID 39513043, 2024). "Despite its limitations, this study proposes the potential role of GDNF as an early diagnostic marker for Parkinson’s disease, aiming to provide a more robust theoretical foundation for subsequent clinical practice." (PMID 39513043, 2024). "Macrophage delivery of GDNF improves motor and non‐motor dysfunction, reduces dopaminergic neuron loss, and preserves axonal terminals in mouse models of Parkinson's disease." (PMID 36914965, 2023). "GDNF was also regarded as the main remedy for neurodegenerative disorders, particularly Parkinson’s disease, as well as other resources causing neuronal death such as ischemic stroke or brain trauma." (PMID 34634077, 2021). "In a study on monkeys with parkinsonism, one of the main side effects of intracerebroventricular injections of recombinant human methionyl-GDNF was weight loss." (PMID 30245717, 2018). "Vitamin D increases GDNF levels in glia and primary neurons, as well as in the striatum of both healthy and Parkinson’s disease rodent models; notably, GDNF depletion occurs in the brain of vitamin D-deficient rats." (PMID 29562608, 2018). "In the brain dopamine system, GDNF-based therapy is rising in treatment of Parkinson’s disease (PD) which is caused by cell death in the substania nigra pars compata (SNpc) of the midbrain, due to loss of dopamine." (PMID 29617307, 2018). "GDNF is protective against the loss of dopaminergic neurons in animal models of Parkinson's disease, and GDNF reduces the number of apoptotic bodies in DRG explants from adult mice." (PMID 15667652, 2005). "The loss of GFRA and GDNF is associated with NDDs, including Parkinson’s disease." (PMID 39203863, 2024). "Pre-clinical and clinical studies to determine the feasibility and safety of CNS- or substantia nigra-targeted GDNF treatment for Parkinson’s disease reported body weight loss and reduced food intake as possible side effects in rats, non-human primates, and humans." (PMID 35806073, 2022). "Furthermore, GDNF has been reported to be associated with aging and various diseases such as Alzheimer's, Huntington's, and Parkinson's diseases, as well as several neuropsychiatric disorders." (PMID 33688499, 2021). "GDNF was isolated from a glial cell line related to the survival of midbrain dopaminergic neurons, and its loss is associated with neurodegenerative diseases like Parkinson’s disease." (PMID 29617307, 2018). "GDNF was originally identified as a factor that promotes the survival of cultured midbrain dopaminergic neurons and reduces the loss and degeneration of these neurons in multiple rodent and primate models of Parkinson's disease." (PMID 28911883, 2017). "Glial-derived neurotrophic factor (GDNF) is essential for regulating dopamine (DA) release in the basal ganglia and for the survival of dopaminergic neurons; GDNF-deficient mice are considered an animal model for aging-related Parkinsonism." (PMID 27445722, 2016). "Executive function impairments demonstrated in GDNF-deficient mice are also relevant to Parkinson’s Disease (PD), since GDNF-deficient mice are considered an animal model for aging-related Parkinsonism, exhibiting accelerated aging-related decline of DA and motor function." (PMID 27445722, 2016). "BDNF is increasingly preferred over GDNF in various Parkinson’s disease therapy models due to its broader neuroprotective profile and practical advantages in delivery." (PMID 41199384, 2025).
Parkinson disease (continued). "Initially identified in the supernatant of a rat glioma cell line as a trophic factor for embryonic midbrain dopaminergic neurons, GDNF has since been extensively studied for its role in dopaminergic neuron protection in Parkinson’s Disease." (PMID 40456763, 2025). "In the central nervous system, GDNF exerts protective effects on dopaminergic neurons—highlighted in Parkinson’s disease research—and shows promise for modulating schizophrenia, depression, and addiction." (PMID 40642294, 2025). "For example, a recombinant adenovirus expressing GDNF under the GFAP promoter was injected into the striatum of a Parkinson’s disease rat model, demonstrating neuroprotective effects." (PMID 40456763, 2025). "NAI has shown potentials in protecting dopaminergic neurons in Parkinson’s disease models by increasing neurotrophic factors such as glial cell line-derived neurotrophic factor (GDNF) and reducing inflammation." (PMID 40356950, 2025). "It has been suggested that GDNF is vital for dopaminergic neurons and is a promising candidate for the treatment of Parkinson's disease." (PMID 40904189, 2025). "Reactive astrocytes in Parkinson’s disease models also exhibit neurotrophic functions, with Nestin-positive astrocytes expressing GDNF." (PMID 40642294, 2025). "It highlighted its role in reducing neuronal inflammation and apoptosis while enhancing BDNF/GDNF-related and dopaminergic signaling pathways in the nigrostriatum of Parkinson’s disease animal models." (PMID 39844853, 2024). "In a trial for Parkinson’s disease, biodegradable implants loaded with GDNF were implanted near dopaminergic neurons, providing sustained neuroprotection and motor function improvements over months." (PMID 39769374, 2024). "A1 neurotoxic astrocytes were significantly increased and GDNF was significantly decreased in neurodegenerative diseases such as Parkinson's disease." (PMID 39095693, 2024). "The seminal role of GDNF in the maintenance and survival of dopaminergic neurons has impelled several studies aiming to treat Parkinson’s disease with this neurotrophic factor." (PMID 38674063, 2024). "The BDNF/GDNF pathway was commonly regulated by exercise training in the nigrostriatum of various Parkinson’s models, providing neurotrophic support by upregulating BDNF and GDNF proteins and downregulating MAPK and p-Erk1/2, thus facilitating CREB activation." (PMID 39844853, 2024). "This suggests a potential link between GDNF and disease severity in MS, similar to its role in other neurodegenerative conditions like Parkinson’s disease and Alzheimer’s disease." (PMID 39451573, 2024). "Here, we use GDNF conditional hypermorph and GDNF conditional knock-out mice to study the role of endogenous GDNF in a mouse model of Parkinson’s disease." (PMID 36690469, 2023). "This reinforces the importance of further developing new therapeutic strategies aiming at providing GDNF or enhancing its expression in the brain regions affected by Parkinson’s disease." (PMID 38201277, 2023). "On this basis, recombinant GDNF protein has been trialled in the treatment of late-stage human Parkinson’s disease patients with only limited success that is likely due to a lack of viable receptor targets in an advanced state of neurodegeneration." (PMID 37410316, 2023). "Several studies also reported that GDNF regulates brain cells' survival and improves their functioning in Parkinson's disease therapy." (PMID 37833789, 2023). "Several studies have described the role of GDNF in central nervous system diseases such as brain cancer and Parkinson's disease." (PMID 37833789, 2023). "SN and striatum receiving direct glial cell-derived neurotrophic factor (GDNF) delivery diminish Parkinsonian symptoms in toxin models of Parkinsonism along with neurite sprouting." (PMID 36909056, 2023). "In a follow-up study, BPNs loaded with glial cell-line derived neurotrophic factor (GDNF) pDNA were used to treat Parkinson’s disease in a 6-OHDA-induced rat model." (PMID 37485250, 2023).
Parkinson disease (continued). "There is a wealth of evidence that GDNF can protect, restore, and augment dopaminergic function in the nigrostriatal pathway in acute animal models of Parkinson’s disease." (PMID 37410316, 2023). "The mechanistic basis for GDNF-dependent cell adhesion is unexplained despite the importance of understanding GDNF function as a promising treatment for Parkinson’s disease." (PMID 37985758, 2023). "Neurotrophic factors, including glial cell line-derived neurotrophic factor (GDNF), have been shown to have positive effects on dopaminergic neurons in pre-clinical models of Parkinson's disease." (PMID 37841347, 2023). "GDNF itself has for decades been known to have potent effects on dopamine system function and survival in models of Parkinson’s disease." (PMID 37238631, 2023). "Since then, in vitro and in vivo studies recognized the potential of GDNF as a protective and restorative factor for DA neurons and, consequently, as a promising therapeutic agent in Parkinson’s disease (PD)." (PMID 38201277, 2023). "GDNF is identified as being important for preserving the health of dopaminergic neurons, with implications for Parkinson’s disease, but there appears to be limited clinical success of exogenously administered GDNF." (PMID 37237908, 2023). "This mouse strain develops parkinsonism in old age with a strong deficit of GDNF signaling which is rescued following the administration of the GM1 analog, LIGA20." (PMID 35064857, 2022). "Exercise can increase the striatal level of GDNF in the Parkinson’s disease (PD) mice model which will attenuate L-3,4-dihydroxyphenylalanine (L-DOPA) -induced dyskinesia." (PMID 36389059, 2022). "Neurotrophic factors, such as BDNF and GDNF, are well-known regulators of the dopamine system and are described as candidates for treating Parkinson’s disease as they exhibit dual neuroprotective and neurogenic properties." (PMID 35431833, 2022). "It promotes differentiation, maintenance, and survival of dopaminergic neurons, prompting the idea of enhancing GDNF expression and action as a therapeutic approach to treat Parkinson’s disease." (PMID 35806073, 2022). "In the Parkinson diseases (PD) model, GDNF specifically increases the expression of miR-182-5p and miR-183-5p in primary midbrain neurons." (PMID 36569394, 2022). "Current opinions about GDNF hold that it supports and regulates midbrain DaN, and confers neuroprotection against toxic insults in the Parkinsonism animal models." (PMID 35283752, 2022). "In this regard, several clinical studies have been conducted to assess the efficacy of GDNF administration by intracerebral injections in improving Parkinson’s symptoms or even counteracting disease progression." (PMID 35645300, 2022). "NLC treatment increased GDNF levels, restored motor activity, increased TH expression, and modulated the microgliosis present in a model of Parkinson’s disease." (PMID 35300705, 2022). "Growth factors such as GDNF have been shown to promote neuroprotection from the toxic insult and regeneration of neurons damaged by Parkinson’s disease." (PMID 36231071, 2022). "The injection of GDNF-modified MSCs derived from rat BM can significantly increase the mean dopamine level in the striatum of lesioned rats and attenuate symptoms of Parkinson’s disease (PD) rats." (PMID 39872744, 2022). "The results show that delivering PLs-GDNF-MBs into the brains of the rats with Parkinson’s disease using an MRI-guided focused ultrasound helps to ameliorate behavioral impairments and neuron loss." (PMID 36365243, 2022). "Novel molecular insights from this study will facilitate the development of edaravone-based therapies (e.g. edaravone/GDNF combination therapy) for ALS and likely other brain disorders associated with neurodegeneration (e.g. Parkinson’s disease and stroke)." (PMID 35012575, 2022).
Parkinson disease (continued). "For example, Barry Hoffer and later Anders Björklund with colleagues experimentally studied GDNF as an agent restoring dopamine neurons in animal models of Parkinson’s disease and obtained quite promising results." (PMID 34634077, 2021). "GDNF was originally discovered as a survival factor for midbrain dopaminergic neurons and a candidate anti-Parkinson disease agent, thereafter focusing research on GDNF receptors on the SNpc and VTA areas that harbor these cells." (PMID 34748545, 2021). "They tested this by delivering the gene for glial-derived neurotrophic factor (GDNF) to the striatum in a rat model of Parkinson’s disease." (PMID 33794355, 2021). "GDNF delivery through hydrogel scaffolds has previously been shown to increase regeneration and nerve repair, and pre-treatment of progenitor cells with GDNF improves cell survival following transplantation in a rodent Parkinson’s disease model." (PMID 34774094, 2021). "Ten individuals with Parkinson’s were unilaterally implanted with a tube to administer GDNF to the putamen in this phase I research." (PMID 33716718, 2021). "Treatment with PLs-GDNF-MBs alleviated behavioral defects in Parkinson’s rats and increased the expressions of GDNF and Nurr1 to protect neurons." (PMID 34576594, 2021). "An exogenous infusion of GDNF into the striatum in a mouse model of Parkinson’s disease prevented the degeneration of A9 dopaminergic neurons in the substantia nigra, which points to the retrograde transport of GDNF." (PMID 34634077, 2021). "Exogenously provided GDNF can promote survival of midbrain dopaminergic neurons, both in vitro and in animal models of Parkinson disease and therefore has been tested in clinical trials for that disease." (PMID 34748545, 2021). "When all these GDNF clinical trials were going on, other members of the GDNF neurotrophic factor family were being studied in Parkinson’s models especially Neurturin in the context of gene therapy." (PMID 33716718, 2021). "The role of GDNF in the treatment of Parkinson's disease is currently being investigated through clinical trials." (PMID 33688499, 2021). "Patients receiving GDNF showed a 30–60% improvement in the off-medication motor sub-score of the Unified Parkinson’s Disease Rating Scale (UPDRS) and a 61% improvement in the activities of daily living sub-score." (PMID 33802760, 2021). "The therapeutic effect of GDNF has been validated in central nervous system (CNS) diseases such as Parkinson’s disease and seizures." (PMID 34696680, 2021). "In an experimental model of Parkinson’s disease, catalpol increases the concentration of striatal dopamine and the level of glial cell-derived neurotrophic factor (GDNF), thereby exerting its neuroprotective functions." (PMID 33708131, 2021). "Unproductive clinical trials of GDNF for Parkinson’s disease treatment have induced to study this failure." (PMID 34634077, 2021). "Cell biology approaches have been central to the effort to use glial cell line–derived neurotrophic factor (GDNF) family ligands to treat Parkinson’s disease." (PMID 32725425, 2020). "Two members of the GFL, GDNF and neurturin, have been evaluated in clinical trials for the treatment of Parkinson’s disease (PD)." (PMID 32046031, 2020). "These cells secrete many growth factors, such as glial-derived neurotrophic factor (GDNF) that was used to treat Parkinson’s disease, and cell differentiation factors." (PMID 33081326, 2020). "On other hand, microglial GDNF expression has been reported to have beneficial effects in Parkinson’s disease and other animal models of inflammation." (PMID 32046031, 2020). "We compare and contrast the use of data visualisations against traditional frequency table reporting, using published AE information in two placebo-controlled trials, of remdesivir for COVID-19 and GDNF for Parkinson disease." (PMID 33353566, 2020).